SMAD1 (SMAD family member 1)
Diseases named in the same sentence as SMAD1 in open-access papers (continued):
Sharing a sentence is not in itself a finding about the gene and the disease.
osteosarcoma (8 papers, 2015 to 2025). A usually aggressive malignant bone-forming mesenchymal neoplasm, predominantly affecting adolescents and young adults. "It was shown that 20 dynes/cm2 shear force significantly induces Smad1/5 phosphorylation in human MG63 osteosarcoma cells within 1 h of treatment, and this induction was returned to the basal level after 4 h of treatment." (PMID 32630668, 2020). "The present study surprisingly found an induction of SCD-1 levels in human osteosarcoma cells under high shear force stimulation through Smad1/5-PPARδ signaling, which consequently affects the osteosarcoma survival (differentiation and cell death)." (PMID 32630668, 2020). "Smad1 or Smad5 gene knockdown in MG63 osteosarcoma cells blocked the PPARδ protein expression of 20 dynes/cm2 shear force induction." (PMID 32630668, 2020). "We found that 20, but not 2, dynes/cm2 shear force surprisingly increases the SCD-1 levels in human MG63 osteosarcoma cells through the activation of Smad1/5 signaling and PPARδ transcriptional factor." (PMID 32630668, 2020). "Smad1 or Smad5 gene knockdown in human MG63 osteosarcoma cells also blocked the PPARδ transcription activation." (PMID 32630668, 2020). "Duan and co-workers found that downregulation of miR-26b in osteosarcoma elevates the levels of CTGF and Smad1, facilitating metastasis in osteosarcoma (os)." (PMID 27078844, 2016). "Additionally, UBE2V1 promotes osteosarcoma differentiation through Smurf1-dependent ubiquitination and subsequent degradation of Smad1." (PMID 41446875, 2025). "The data from our previous and present studies demonstrated that high shear force could inhibit differentiation and initiate cell death of the cancer cells, including the human MG63 osteosarcoma, through Smad1/5 signaling." (PMID 32630668, 2020). "For target proteins, we exploit CRISPR/Cas9 to rapidly generate human kidney HEK293 and U2OS osteosarcoma homozygous knock-in cells harbouring GFP tags at the VPS34 (vacuolar protein sorting 34) and protein associated with SMAD1 (PAWS1, aka FAM83G) loci, respectively." (PMID 27784791, 2016). "Thus, we examined whether Smad1/5 signaling also affects 20 dynes/cm2 shear force-induced SCD-1 expression in human MG63 osteosarcoma cells." (PMID 32630668, 2020). "Smad1 and Smad5 gene knockdown significantly inhibited SCD-1 protein expression of 20 dynes/cm2 shear force induction in MG63 osteosarcoma cells." (PMID 32630668, 2020). "To investigate whether the formation of homomeric ALK2-R206H complexes correlates with aberrant signaling by ActA to SMAD1/5/8, we conducted signaling studies in U2OS osteosarcoma cells, which respond well to ActA signaling." (PMID 38334613, 2024). "A SCD-1 upregulation in human MG63 osteosarcoma cells under 20, but not 2, dynes/cm2 shear force stimulation was shown, and this induction was regulated by Smad1/5 and peroxisome proliferator-activated receptor δ (PPARδ) signaling." (PMID 32630668, 2020).
gastric cancer (7 papers, 2016 to 2023). A primary or metastatic malignant neoplasm involving the stomach. "Analysis showed that high expression levels of SMAD1, SMAD2, and SMAD4 are associated with a better survival rate of gastric cancer patients, whereas SMAD3, SMAD5, SMAD6, SMAD7 and SMAD9 are associated with poor prognosis." (PMID 34138687, 2021). "SMAD1, SMAD2, and SMAD4 are associated with favorable OS in the first and third stage of gastric cancer." (PMID 34138687, 2021). "High expression level of SMAD1 showed better prognostic value in gastric cancer with moderate differentiation." (PMID 34138687, 2021). "This study shows that high expression level of SMAD1, SMAD2, and SMAD4 is associated with favorable OS of gastric cancer patients." (PMID 34138687, 2021). "The prognostic value of SMAD1 mRNA expression in gastric cancer was explored." (PMID 34138687, 2021). "Therefore, rhBMP-2 appeared to stimulate the activation of BMPRII, which stimulated the expression of p-Smad1/5/8 proteins in gastric cancer cells." (PMID 27636990, 2016). "Studies have shown that SMAD1 is highly expressed in cisplatin-resistant gastric cancer cells and that SMAD1 interacts with YAP1, leading to the increased resistance of gastric cancer cells to cisplatin." (PMID 37685308, 2023). "The high expression of SMAD1, SMAD2, and SMAD4 in gastric cancer tissues is significantly correlated with the prognosis of patients." (PMID 36969909, 2023). "Collectively, these results demonstrate that the high expression level of three members of SMADs (SMAD1, SMAD2, and SMAD4) is significantly correlated with favorable OS of gastric cancer patients, which is opposite to SMAD3." (PMID 34138687, 2021). "The results showed that the high expression of three members of SMADs (SMAD1, SMAD2, SMAD4) was correlated with afavorable OS of gastric cancer patients." (PMID 34138687, 2021). "Exposure of LNT-229 or LN-308 cells to recombinant GDF-15 did not trigger Smad2 or Smad1/5/8 phosphorylation, a finding that is in line with previous reports in gastric cancer cells." (PMID 26741507, 2016).
liver cancer (7 papers, 2013 to 2023). An epithelial or non-epithelial malignant neoplasm that arises from the liver. "In bladder cancer, hsa-miR-26b prevents tumor migration and invasion by regulating the PLOD2 gene and it performs a similar function by targeting the SMAD1 gene in liver cancer." (PMID 36820950, 2023). "In summary, we demonstrated for the first time that proHp suppresses the TGF-β-induced EMT and cell invasion in vitro by enhancing Smad1/5 activation and suppressing the Smad2/3 signaling pathway in SK-Hep1 liver cancer cells." (PMID 35580109, 2022). "BMP-9 has been shown to activate Smad-dependent pathways through Smad1/5/8 to cause ID1 up-regulation and growth promotion in HepG2 liver cancer cells." (PMID 27650540, 2016). "It is necessary to clarify the function of Smad1/5/8 and the interactions of the Smad2/3 and Smad1/5/8 pathways during the TGF-β-induced EMT and cell invasion in liver cancer." (PMID 35580109, 2022). "After mouse liver cancer cell Hepa1-6 was exposed to BBR, the Smad1/5/8 pathway can be activated to promote the expression of hepcidin." (PMID 34356769, 2021). "In the liver cancer cell line HepG2, BMP9 triggers Smad1,5,8 phosphorylation and inhibitor of DNA binding 1 (Id1) expression up- regulation." (PMID 23936038, 2013).
renal fibrosis (7 papers, 2013 to 2024). A final common manifestation of a wide variety of chronic kidney diseases characterized by glomerulosclerosis and tubulointerstitial fibrosis. "Furthermore, in vivo L-Endoglin overexpression potentiates Smad1 and Smad3 pathways and this effect is associated with higher renal fibrosis development." (PMID 25313562, 2014). "However, Smad1 pathway activation has been recently associated with renal fibrosis in diabetic and obstructive nephropathy." (PMID 25313562, 2014). "To elucidate how L-ENG overexpression contributes to increased renal fibrosis, we assessed Smad1 and Smad3 phosphorylation by measuring the abundance of p-Smad1 and p-Smad3 by western blot and immunohistochemistry." (PMID 25313562, 2014). "The expression of genes that promote renal fibrosis (Smad2, Smad3, Smad4, Shh, Dll1) was downregulated, while the expression of genes that inhibit renal damage (Smurf1, Smurf2, Smad1, Smad5, Smad6, Smad7) was increased in the WT+miPEP31 group (PEP1/2) compared with the WT+ cPEP (SCR1/2) group." (PMID 38992718, 2024). "The TGF-β signaling pathway was also enriched in the present study, and the expressions of Smad1, Smad6, and Smad7 were significantly upregulated, which might indicate channel catfish renal fibrosis." (PMID 35747138, 2022). "Herein, we asserted that BMP-7 upregulates SnoN mRNA and protein levels by activating the classical Smad1/5 pathway to refrain from the partial EMT of RTECs and the deposition of ECM in diabetes-induced renal fibrosis." (PMID 35314669, 2022). "Many studies have demonstrated that TGF-β promotes renal fibrosis through EMT by activation of Smad2/3 and was counteracted with BMP-7 by motivation of Smad1/5/8 to maintain the epithelial phenotype of TECs." (PMID 24350257, 2013).
lymphoma (6 papers, 2010 to 2024). A malignant (clonal) proliferation of B- lymphocytes or T- lymphocytes which involves the lymph nodes, bone marrow and/or extranodal sites. "Moreover, SMAD1 modulates lymphoma cell’s response to TGFB with SMAD1 knockdown or mutational inactivation associated with resistance to antiproliferative effects of TGFB." (PMID 35406544, 2022). "In summary, our data demonstrate that PRC2 inhibition or deletion results in the upregulation and activation of BMP‐ACVR1 signaling through phosphorylation of SMAD1/5 in multiple PRC2 drug‐sensitive lymphoma cells and xenograft tumors." (PMID 38229201, 2024). "Further, SMAD1, in the family of transforming growth factor-beta, was shown to be hypermethylated and silenced in the resistant lymphoma cell lines." (PMID 25480665, 2014). "The correlation between BMP-induced phosphorylation of Smad1/5/8 and suppression of DNA synthesis in the various lymphoma cell lines was significant when all the different BMPs were combined (p = 0.015, adjusted R-square = 40%)." (PMID 23049692, 2012). "In the future, therapies which can restore sensitivity of lymphoma cells to TGF-β growth control by inducing Smad1/5 signalling can be helpful in treatment of B-cell lymphoma patients." (PMID 21092277, 2010). "This was found to be correlated with increased expression of SMAD1, a signal transducer protein involved in multiple signaling pathways, by the DNA methylating agent azacytidine, leading to the sensitization of lymphoma cells to genotoxic effect of doxorubicin." (PMID 28881739, 2017). "Sensitivity to growth inhibition by TGF-β might depend on Smad1/5 signalling in lymphoma cell lines, which possibly initiates via Alk-5 and terminates in up-regulation of Id1 and other target genes." (PMID 21092277, 2010). "Accordingly, DP DLBCL was enriched for SMAD1 methylation, providing a mechanism for DLBCL to overcome the potential anti-lymphoma role of TGFB mediated secreted by surrounding stroma." (PMID 35406544, 2022). "Collectively, BMP-induced phosphorylation of Smad1/5/8 correlated with the functional effects of BMPs in lymphoma cell lines, suggesting that BMP-resistance mechanisms in lymphoma are upstream of R-Smad activation." (PMID 23049692, 2012). "Together, the removal of H3K27me3 marks through PRC2 inhibition or depletion results in the upregulation of ACVR1 and the activation of BMP‐ACVR1 signaling, reflected by the phosphorylation of SMAD1/5 and the common upregulation of ID2 or ID3 in EZH2‐mutant lymphoma cells." (PMID 38229201, 2024). "This implies that the mechanism of resistance also can be found downstream of Smad1/5/8 phosphorylation, and that lymphoma cells can develop different ways to escape the negative influence of BMPs." (PMID 23049692, 2012). "Tumor specimens from three out of five lymphoma patients were also resistant to BMPs, as determined by no activation of the BMP effectors Smad1/5/8." (PMID 23049692, 2012).
scleroderma (6 papers, 2011 to 2025). Scleroderma is a rare autoimmune connective tissue disorder characterized by abnormal hardening of the skin and, sometimes, other organs. "The positive effect of endoglin is even more interesting considering that in scleroderma fibroblasts the fibrogenic gene program is mediated via activation of Smad1 and ERK1/2 pathways, which are positively regulated by endoglin." (PMID 23437087, 2013). "For example, a strong correlation between collagen and CCN2 expression levels, and Smad1 activation status was observed in hTERT immortalized scleroderma clones and blockade of Smad1 in scleroderma fibroblasts normalized collagen and CCN2 production by these cells." (PMID 21760921, 2011). "In scleroderma fibroblast, ALK1/Smad1/5 was reported to promote the production of extracellular matrix proteins such as collagen I and connective tissue growth factor." (PMID 36091775, 2022).
asthma (5 papers, 2020 to 2024). "Impairment of the antifibrotic TGFβ/Smad1/5/8 pathway in HBF from asthma donors correlates with enhanced FMT." (PMID 39578779, 2024). "The expression of TGF-β1, TβR1 and Smad1 was significantly increased in the asthma group, but was decreased in the mycobacterium nebulization group." (PMID 32834825, 2020). "Compared with the normal group, the expression of TGF-β1, T βR1, and Smad1 IOD values was significantly increased in the asthma group (P < 0.01), and significantly decreased in the mycobacterium nebulization group (P < 0.01)." (PMID 32834825, 2020). "In the asthma model of Macaca mulatta, exposure to house dust mite (HDM) allergens and ozone significantly downregulated p-Smad1/5/8 level in the airway epithelium." (PMID 39578779, 2024). "Activation of anti-fibrotic Smad1/5/8 signaling downregulates genes for pro-fibrotic factors such as α-SMA and fibronectin as a way to prevent FMT in HBF from asthma donors." (PMID 39578779, 2024). "Antifibrotic TGF-β/Smad1 pathway activation is downregulated in fibroblasts; however, profibrotic TGF-β/Smad2/3 pathways are upregulated in patients with asthma." (PMID 37569643, 2023). "Therefore, both possibilities should be considered: the change in Smad1 protein expression may be dependent or independent of the ongoing underlying inflammation factors in asthma." (PMID 35800124, 2022). "The eosinophil count; protein expression of TGF-β1, TβR1, and Smad1; and percentages of CD3+γδT and IL-13+CD3+T cells were significantly lower in the M. vaccae nebulization group than in the asthma control group (P < 0.01)." (PMID 32834825, 2020). "The aim of the present study was to evaluate whether enhanced asthma-related TGF-β1 FMT is the result of the differential activation of the profibrotic TGF-β/Smad2/3 and antifibrotic TGF-β/Smad1/5/9 signalling pathways in HBFs." (PMID 33020537, 2020). "We reported that TGF-β/Smad1/5/9 pathway activity is increased in HBFs from non-asthmatic donors compared to HBFs obtained from patients with asthma." (PMID 33020537, 2020). "However, TGF-β1 stimulation strongly decreased Smad1 but not Smad5 contents in HBFs from patients with asthma." (PMID 33020537, 2020).
granulosa cell tumor (5 papers, 2017 to 2021). A slow-growing, malignant tumor, characterize by the presence of granulosa-like cells and Call-Exner bodies, that is almost always found in the ovary. "For R-Smads, SMAD1 regulated COV434 cell (a human granulosa cell tumor-derived cell line) apoptosis, and SMAD5 suppressed human granulosa cell apoptosis via the FasL-Fas pathway, but SMAD8 has not been reported to regulate GC apoptosis." (PMID 31167348, 2019).
non-small cell lung carcinoma (5 papers, 2011 to 2020). A group of at least three distinct histological types of lung cancer, including non-small cell squamous cell carcinoma, adenocarcinoma, and large cell carcinoma. "LKB1 protein expression and Smad1 phosphorylation analysis in a cohort of non-small cell lung cancer patients demonstrated a negative correlation predominantly in a subset enriched in adenocarcinomas." (PMID 26701726, 2016).
anemia (4 papers, 2016 to 2021). A reduction in the number of red blood cells, the amount of hemoglobin, and/or the volume of packed red blood cells. "In many models of anemia of inflammation, IL-6 has been shown to be a primary driver for hepcidin induction and the SMAD1/5/8 pathway is also known to contribute, likely via activin B and STAT-3-SMAD interactions at the hepcidin promoter." (PMID 34873429, 2021). "The data indicate that HFE overexpression induced Smad1/5 phosphorylation, hepcidin mRNA expression, and development of anemia." (PMID 30271947, 2018). "HFE overexpression in control mice results in increased hepatic hepcidin levels, p-Smad1/5 levels, and iron deficiency anemia, whereas overexpression of HFE in hepatocyte-specific Alk3-deficient mice results in no change in hepcidin, p-Smad1/5 levels, or blood parameters." (PMID 30271947, 2018).
B-cell lymphoma (4 papers, 2010 to 2022). "Smad1 is the transcriptional regulator of the sphingosine phosphate receptor S1pr2, and this tumor suppressive pathway is inactivated in B cell lymphoma." (PMID 36042317, 2022). "A similar effect has been described for Smad1 in a B-cell lymphoma cell line after stimulation with TGF-ß." (PMID 23560048, 2013). "We suggest that phosphorylation of Smad1/5 is important for the anti-proliferative effects of TGF-β in B-cell lymphoma." (PMID 21092277, 2010). "Taken together, the data suggest that Smad1/5 is involved in controlling the anti-proliferative effects of TGF-β in B-cell lymphoma cell lines." (PMID 21092277, 2010). "In conclusion, we have shown that some B-cell lymphomas can escape BMP-induced antiproliferative effects and that this correlates with reduced Smad1/5/8 activation." (PMID 23049692, 2012).
Cerebral ischemia (4 papers, 2015 to 2025). Restriction of arterial blood supply to the brain associated with insufficient oxygenation to support the metabolic requirements of the tissue. "Knockdown of GAS5 was also shown to reduce apoptosis and inflammation in cerebral ischemia/reperfusion injury through interaction with miR-26b-5p and the regulation of Smad1 expression." (PMID 38132140, 2023). "To study the role of Smad1 in cerebral ischemia, we generated Smad1 conditional knockout mice (cKO) with Smad1 ablation in all neural cells in the CNS (Smad1fl/-; Nestin-Cre)." (PMID 26317208, 2015). "Downstream targets of Smad1 in the setting of cerebral ischemia remain to be identified, but may include regulators of redox homeostasis, as ROS levels and nucleotide oxidation are lower in ischemic tissue in the absence of Smad1." (PMID 26317208, 2015). "Whether Smad1 is also involved in activating neural progenitors after cerebral ischemia awaits further study." (PMID 26317208, 2015). "Finally, in cerebral ischemia, Smad1 may mainly function as a downstream effector of canonical BMP signaling, or alternatively, as a mediator of other stroke-induced signaling pathways, such as brain-derived neurotrophic factor (BDNF) or GSK3β signaling." (PMID 26317208, 2015).
colon cancer (4 papers, 2015 to 2021). "All these results demonstrate that Dragon acts through the Erk1/2 and Smad1/5/8 pathways to induce colon cancer proliferation." (PMID 26029998, 2015). "All these results suggest that Dragon activates Smad1/5/8 and Erk1/2 in colon cancer cells both in vitro and in vivo." (PMID 26029998, 2015). "Dragon promotes colon cancer cell proliferation and tumor growth via the Smad1/5/8 and Erk1/2 signaling pathways." (PMID 26029998, 2015). "To determine whether Smad1/5/8 and Erk1/2 mediate Dragon's action on colon cancer cell proliferation, we used the BMP pathway inhibitor LDN193189 and the Erk1/2 inhibitor U0126." (PMID 26029998, 2015). "In conclusion, our present study reveals that Dragon stimulates colon cancer growth via the BMP4 and the downstream Smad1/5/8 and Erk1/2 pathways both in vitro and in vivo." (PMID 26029998, 2015).
diabetes (4 papers, 2017 to 2024). "However, no study performed to date has assessed regulatory mechanisms underlying the significance of the phosphorylation of the Smad1 linker domain in diabetes mellitus." (PMID 30002389, 2018). "All the data were obtained under a diabetic condition, indicating that TGF-β–Smad3 signaling modulates the phosphorylation of the Smad1 C-terminal and linker domains simultaneously in diabetes mellitus." (PMID 30002389, 2018). "Moreover, it was reported that rats with diabetes exhibited markedly increased renal Smad1 and collagen IV expression and extracellular matrix deposition." (PMID 28886733, 2017).